EPCAM (epithelial cell adhesion molecule)
Diseases named in the same sentence as EPCAM in open-access papers (continued):
Sharing a sentence is not in itself a finding about the gene and the disease.
metastatic disease (continued). "Blood was obtained at the time of first diagnosis of metastatic disease or disease progression and analyzed for CTCs using the AdnaTest BreastCancer (QIAGEN Hannover GmbH, Germany) for the expression of EpCAM, MUC-1, HER2, ER and PR." (PMID 27456970, 2016). "Even if each tumour is composed of a mixture of heterogeneous tumour cells, the released EpCAM+ and EpCAM+CD147+ taMPs can be reliable detected in the circulation in both primary and metastatic tumour-bearing patients." (PMID 27127176, 2016). "In contrast, two out of three patients with metastatic disease at diagnosis (#4 and #10) showed an elevated number of single CTCs in both EpCAM‐positive and EpCAM‐low/negative fractions, but were negative for CTC clusters." (PMID 35212153, 2022). "In contrast to EpCAM, which is thought to be downregulated as neoplastic cells begin to exhibit a mesenchymal phenotype, PSMA is largely specific to prostate cells while its expression increases progressively in higher grade PC, metastatic disease and CRPC." (PMID 22558290, 2012). "The two-color immunofluorescence staining with anti-CXCL16 and anti-EpCAM mAb and consecutive-sections-staining procedure with anti-CEA and anti-CXCL16 in the primary tumor tissues and lymph node metastasis suggest that CXCL16 is produced mainly by primary tumor cells and metastatic tumor cells." (PMID 31752131, 2019). "Notably, we found that proteins involved in triple‐negative breast cancer (TNBC), such as GSTP1 and EPCAM, were enriched in ERα‐N metastatic tumours, while proteins typically upregulated in ERα‐P disease, such as ALCAM and KRT18, were enriched in ERα‐P as well as the ERα‐C metastatic tumours." (PMID 37854018, 2024). "Recently, the presence of both epithelial and quasi-mesenchymal subtypes of cancer cells was identified in PDAC42; selection strategies targeting EpCAM only may not fully recapitulate the primary/metastatic tumor and provide insufficient information for patients with a non-epithelial PDAC subtype." (PMID 29657983, 2017). "We assessed the ratio of RON, phosphorylated mTORC1, and phosphorylated rpS6 to the epithelial marker EpCAM and did not see a direct correlation between high levels of total RON protein and levels of activated mTORC1 or rpS6 in primary or metastatic disease." (PMID 30456298, 2018). "Disseminated EpCAM-negative CTCs undergo mesenchymal-epithelial transition (MET) at distant organs, invade the tissue and then become localized to generate metastatic tumors." (PMID 26631983, 2015). "Finally, all RMS patients with metastatic disease at baseline had at least 1 CTC, if we included EpCAM‐positive and/or EpCAM‐low/negative events." (PMID 35212153, 2022).
endometrial cancer (39 papers, 2012 to 2025). Primary or metastatic malignant neoplasm involving the endometrium (mucous membrane that lines the endometrial cavity). "They reported a low risk for endometrial cancer in patients with deletions of EPCAM compared to that with a mutation in an MMR gene." (PMID 23938213, 2013). "In this review, DNA hypermethylation associated with endometrial cancer based on epimutation of three genes, hMLH1, hMSH2 and epithelial cell adhesion molecule (EPCAM), and the effects of miRNAs in endometrial cancer will be discussed." (PMID 22548175, 2012). "In addition, EpCAM serves as an invaluable biomarker in the realm of oncology, offering diagnostic capabilities for endometrial cancer and lymph node metastasis detection in early-stage gastric cancer patients." (PMID 38187284, 2024). "EpCAM-based immunoisolation positively detected CTC in high-risk endometrial cancer patients." (PMID 25261936, 2014). "Finally, it should be note that although EpCAM expression was found consistent in primary endometrial carcinomas, its proposed modulation and eventual loss during EMT adds controversy to the efficiency of enrichment of CTC owning a plasticity phenotype." (PMID 25261936, 2014). "Further research is needed to clarify the contribution of EPCAM mutations in endometrial cancer." (PMID 24056992, 2013). "In endometrial cancer, EPCAM deficiency is also involved in hypermethylation of the hMSH2 promoter." (PMID 22548175, 2012). "Unexpectedly, EpCAM plays dual roles in endometrial cancer, promoting cell proliferation and inhibiting invasion." (PMID 38187284, 2024). "We have identified CD45+/CK 8,18,19+/CD31+/EpCAM+/DAPI+-stained CAMLs in more than 98% (63/64) of our tested blood samples in patients with endometrial cancers." (PMID 36230499, 2022). "We report the identification of CD45+/CK 8,18,19+/EpCAM+/CD31+/DAPI+ CAMLs in the blood of patients with endometrial cancers." (PMID 36230499, 2022). "Here, we describe molecular imaging of a near-infrared fluorescently labeled monoclonal antibody targeting epithelial cell adhesion molecule (EpCAM) as an in vivo imaging modality for visualization of orthotopic endometrial carcinoma PDX." (PMID 32041116, 2020). "In our present study EpCAM-AF680 NIRF imaging allowed early detection of metastases in endometrial carcinoma mouse models, indicating that EpCAM is expressed in metastatic lesions." (PMID 32041116, 2020). "To confirm that EpCAM expression is maintained following in vivo passage in immunodeficient mice we isolated cells from a representative PDX model of endometrial carcinoma (PDX2) and performed flow cytometry with an anti-EpCAM antibody." (PMID 32041116, 2020). "Further gynecological tumors from EPCAM 3′-end deletion carriers should be tested to evaluate the usefulness of EPCAM IHC in endometrial carcinomas." (PMID 33003511, 2020). "EGF treatment of endometrial carcinoma cells was reported to induce an EGFR-dependent RIP of EpCAM, resulting in complete EpEX shedding from the membrane and in release of EpICD, which serves as a nuclear transcriptional inducer of an EMT program." (PMID 30261040, 2018). "Recently, Hsu and colleagues provided a link between EGF-induced EMT and RIP of EpCAM in the endometrial carcinoma cell line RL95-2." (PMID 30261040, 2018).
endometrial cancer (continued). "CD44, transglutaminase 2 (TGM2), and epithelial cell adhesion molecule (EpCAM) were identified as novel plasma markers for endometrial cancer diagnosis using the MAGPIX® System, which employs magnetic nanoparticles coated with antibodies and requires a tiny sample volume (25 μL)." (PMID 41440277, 2025). "Similarly, detection of EpCAM positive CTCs with high expression of EMT markers (ETV5, NOTCH1, SNAI1, TGFB1, ZEB1, and ZEB2) was associated with a worse prognosis in endometrial cancer patients." (PMID 34209658, 2021). "In vitro studies showed that Solitomab (MT110), which binds CD3 and targets EpCAM, increased the sensitivity of tumor cells to cytotoxic T cell death in multiple EpCAM positive ovarian and endometrial cancer cell lines including ovarian carcinosarcoma and primary uterine serous papillary carcinoma." (PMID 30249178, 2018). "Studies of canceration of the endometrium and epimutation of genes have mainly focused on hMLH1, hMSH2, and EPCAM. hMLH1 and hMSH2 are DNA mismatch repair (MMR) genes that have a strong association with endometrial cancer, above that of other MMR genes such as hMSH6 and PMS2." (PMID 22548175, 2012). "Combining the tumor-targeting properties of EpCAM with three-dimensional PET/CT technology may create a translational imaging tool that improves the value of both preclinical and diagnostic imaging of endometrial carcinoma." (PMID 32041116, 2020). "In addition, EGF-mediated stimulation cleaves the cytoplasmic domain of EpCam (EpICD) and leads to the internalization and nuclear localization of EpCID, resulting in the transcription of genes involved in migration, adhesion, and epithelial-mesenchymal transition in endometrial cancer." (PMID 37370706, 2023). "EpCAM, TGM2, HE4, CA-125, and IL-33 measured in serum samples from 42 patients with endometrial cancer concerning clinicopathological factors." (PMID 33014844, 2020). "Comparison of the levels of EpCAM, TGM2, IL-33, CA125, and HE4 in pre- and post-operated endometrial cancer patients." (PMID 33014844, 2020). "EPCAM and CAPS were selected for further investigation based on their implication in the development of ovarian and endometrial cancer." (PMID 33384952, 2020). "EpCAMlow CTC have been found significantly associated with tumor depth, lymph node metastasis, and increased malignancy in gastric and endometrial cancers after staining by anti-CD45, anti-EpCAM, anti-CK, and anti-CEA (CD66e) antibodies." (PMID 31636732, 2019). "EGF-mediated RIP of EpCAM was reported to lead to the release of the intracellular domain of EpCAM (EpICD) that, aside from fostering proliferation, induces an EMT program in endometrial carcinoma cells." (PMID 30261040, 2018). "Our study had some limitations, such as the low number of extra-GI primary neoplasms in EPCAM deletion carriers, especially endometrial carcinoma, not allowing to know the usefulness of EPCAM IHC in this type of carcinomas." (PMID 33003511, 2020).
endometrial cancer (continued). "Quantification of immunoblot results did reveal an induction of EpCAM expression levels in Du145 cells treated with 1.8 and 18 nM EGF and RL95-2 endometrial carcinoma cells with 9 nM EGF for 72 hr, and a slight reduction of EpCAM expression following 1.8 and 18 nM EGF treatment of Cal33." (PMID 30261040, 2018). "In the present study, RIP of EpCAM through EGF/EGFR signaling could neither be observed in an array of carcinoma cell lines nor be reproduced in RL95-2 endometrial carcinoma cells, independently of time points and EGF concentrations used." (PMID 30261040, 2018). "In order to confirm that EpCAM was not just aberrantly expressed on cell line cultures and was in fact ubiquitously expressed in primary tumor tissues, we performed immunohistochemical (IHC) analysis of EpCAM staining on a cohort of 153 endometrial carcinoma patients." (PMID 32041116, 2020). "Unlike the findings observed in endometrial cancers, EGF treatment had minimal effects on RIP of EpCAM." (PMID 34209658, 2021). "Further evaluation of the same panel in the endometrial carcinoma cell lines AN3CA, Hec1B and RL95-2 was performed in order to verify that the high EpCAM expression was not a unique feature of Ishikawa cells." (PMID 32041116, 2020).
breast tumor (31 papers, 2004 to 2024). "Concerning EpCAM, its over-expression was observed in up to 70% of breast tumors in which it strongly correlates with a higher risk of recurrence." (PMID 28870198, 2017). "Across the 112 684 cells analysed from primary breast tumours, a similar number of cancer cells expressed epithelial markers (EPCAM, CDH1 and ESR1)." (PMID 37691350, 2023). "Phagocytosis of breast tumor cells was quantified as the proportion of F4/80+ macrophages that contain intracellular EpCAM, a marker of breast tumor cells." (PMID 34054811, 2021). "We studied the expression of stemness genes in the EpCam+ cells derived from the breast tumor of patient St23784/17 with stemness gene amplifications and from the tumor of patient Ti41749/17 with no stemness gene amplifications." (PMID 32523653, 2020). "EpCam+ cells derived from the breast tumor of patient Ti41749/17 were cultivated in a Human EpiCult-C environment." (PMID 32523653, 2020). "An interesting study in primary breast tumor samples showed that EpCAM promotes ERK activity, therefore elucidating novel double-negative feedback between EpCAM and ERK that contributes to EMT regulation." (PMID 31200510, 2019). "Further characterization of the CD24−/CD44+ BCSC-like subset with other stem cell markers revealed that estrogen-induced breast tumor initiating/cancer stem cells acquire additional phenotypes, such as 49f, EpCam, ALDH1, and CD133." (PMID 30486409, 2018). "In this context, CD133 and EpCAM are highly promising target antigens since, beyond to be markers of BCSCs, they have a direct relationship with malignancy of breast tumors." (PMID 28870198, 2017). "On the contrary, analysis on a fresh breast tumor biopsy, by flow cytometry, revealed that IL-17RB was expressed by the EpCAM+ Cytokeratin+ tumor cells and by some fibroblasts, but also immune subpopulations within the tumor microenvironment." (PMID 29371916, 2017). "Silencing EPCAM gene expression in breast tumor cell lines in vitro results in a dramatic decrease in metabolic activity, cell migration and invasion." (PMID 24944582, 2014). "For example, the PD assessment of a freshly resected breast tumor biopsy using a mock FNA approach showed only a small fraction (<1%) of EpCAM & p-Histone H3 positive objects." (PMID 25367255, 2014). "The EpCAM positive p-Histone H3 G2M tumor cell population was readily detectable in two mock FNA samples taken from the same primary breast tumor." (PMID 25367255, 2014). "Among the cancer stem cell markers, CD133 and EpCAM strongly correlate with breast tumor aggressiveness, suggesting that simultaneous targeting of the two surface antigens may be beneficial in treatment of TNBC." (PMID 28870198, 2017). "Among the stemness markers in TNBC, CD133 and EpCAM may be of interest since they have a direct relationship with malignancy of breast tumors." (PMID 28870198, 2017). "Here we correlated the simultaneous expression of CD133 and EpCAM with malignancy of breast tumor cells revealing the unprecedented evidence that a CD133+/EpCAM+ sub-population with more aggressive potential is present in the MDA-MB-231 cell line, showing a basal-B TNBC phenotype." (PMID 28870198, 2017). "In addition, human breast tumor-derived CTCs co-expressing E and M protein markers, such as EPCAM and CD44 have been shown to initiate metastases in mice." (PMID 26020648, 2015). "Gene expression profiling of cell lines that exhibit a large EpCAM+/CD49f+ population most closely corresponded with the expression profile of Basal-like breast tumors suggesting that EpCAM+/CD49f+ cells may be the cellular precursors to both luminal and basal-like tumors." (PMID 20964822, 2010). "Next, adjacent tumor sections were stained for EpCAM and the immune cell markers (CD45, CD3, CD66b, CD56 and CD11b), to determine the immune cells that infiltrate the breast tumors." (PMID 39246414, 2024).
breast tumor (continued). "To directly demonstrate that the hypoxic microenvironment influences the tumor epigenetic landscape in vivo, we applied Pi-ATAC to EpCAM and HIF1α-stained cells in the MMTV-PyMT breast tumor model." (PMID 30389926, 2018). "In invasive lobular carcinomas, the mean percentage of positively stained breast tumor cells in the ovaries was highest for EMA, Her2/neu and EpCAM; specifically, 64, 74 and 68%, respectively." (PMID 28327103, 2017). "Nevertheless, co-staining breast tumors with EpCam did rule out an overlap with Pkg1 for all epithelial populations." (PMID 39741968, 2024). "Further, the molecularly classified basal-like breast tumors have a low or nonexistent expression of EpCAM and have increased expression of mesenchymal markers." (PMID 24602188, 2014). "Two cell surface markers (EpCAM-Pecy7 and CD49f-APC) were used to identify 2 cell subsets using FACS, namely, basal/stem cells (TICs, CD49fhighEpCAMlow, approximately 57.6 %) and luminal cells (NTCs, CD49flowEpCAMhigh, approximately 34.1 %) in primary breast tumor, as reported in a previous study." (PMID 26695440, 2016). "Indeed, in a number of breast tumors, no obvious staining was observed with the EpCAM antibody, while the aptamer showed a moderate positive signal." (PMID 23460885, 2013). "Only 62 transcripts were commonly upregulated in breast tumours against both healthy breast and non-breast tissues, featuring ERBB2, ERBB3, EPCAM, and IGFR." (PMID 38306344, 2024). "In a fourth study, single-cell suspensions of seven patient-derived breast tumors were orthotopically injected into SCID mice; two PDOX tumors developed CTCs as detected by an EpCAM-based platform, and no metastases were observed in any of the seven mice." (PMID 31462307, 2019).
mesothelioma (31 papers, 2006 to 2026). A usually malignant and aggressive neoplasm of the mesothelium which is often associated with exposure to asbestos. "Furthermore, EpCAM expression is limited in rare malignancies with distinct cellular origins, including sarcomas and mesotheliomas." (PMID 40525275, 2025). "Firstly, we quantified by flow cytometry analysis the epithelial marker, Ep-Cam, in mesothelioma cells after Kp-10 treatment; H28 and H2452 cells were treated with 0.1 nM Kp-10 for 48 hours and marked with Ep-Cam antibody which functions as an epithelial cell adhesion molecule." (PMID 29721201, 2018). "Fluorescent immunostaining of human mesothelioma cell lines showed that sarcomatoid CRL-5946 cells expressed COL5A2 and SPARC dramatically higher compared to epithelioid CRL-5915 cells, while CRL-5915 cells expressed epithelial marker EpCAM specifically." (PMID 35046456, 2022). "BerEP4, one of the monoclonal antibodies recognizing EpCAM, has long been used for the diagnosis of mesotheliomas and, therefore, is not very expensive and is available in most hospitals." (PMID 31361893, 2019). "In contrast, using ELISA test, the detection of EpCAM+ MPs was positive in 66% (29/44) of carcinoma pleurisies with 233 pg/ml but also in 3/27 with non-carcinoma malignant pleural effusions (mesothelioma) with a low concentration EpCAM (7 pg/ml)." (PMID 26689993, 2016). "Similarly, lung adenocarcinomas often overexpress EpCAM, whereas mesotheliomas are consistently negative." (PMID 37627911, 2023). "On the other hand, all tumor cells were negative for ESA/EPCAM/(MOC 31), a negative mesothelioma marker commonly used to distinguish mesotheliomas from carcinomas." (PMID 27129173, 2016).